SMAD2 (SMAD family member 2)
Diseases named in the same sentence as SMAD2 in open-access papers (continued):
Sharing a sentence is not in itself a finding about the gene and the disease.
Skeletal muscle atrophy (3 papers, 2014 to 2025). The presence of skeletal muscular atrophy (which is also known as amyotrophy). "Nevertheless, the fact that losartan treatment attenuated the reduction in the relative muscle weight in females suggests that suppressing the AT1 receptor is an effective strategy against disuse-induced skeletal muscle atrophy in female rats by preventing Smad2/3 signaling." (PMID 35264097, 2022). "Akt represses expression of the muscular atrophy inducing E3-ubiquitin ligases MAFbx and MuRF1 through phosphorylation of FoxO transcription factors and conversely the repressive action of Akt on MAFbx and MuRF1 can be lifted by myostatin through SMAD2." (PMID 24963862, 2014).
teratoma (3 papers, 2013 to 2023). A non-seminomatous germ cell tumor characterized by the presence of various tissues which correspond to the different germinal layers (endoderm, mesoderm, and ectoderm). "Here we show that Dnd1Ter/+ germ cells are sensitized to their microenvironment and that low oxygen tension, through the activation of Nodal/Smad2 pathway, promotes misregulation of male germ cell development, leading to teratoma initiation." (PMID 37180974, 2023). "In striking contrast to WT and Smad3−/− teratomas, Smad2−/− teratomas mainly had fibroblasts like tissues and within which scattered with few muscle tissues and endoderm tissues, while neural tube like ectoderm tissues were hardly presented." (PMID 26905010, 2016).
ulcerative colitis (3 papers, 2020 to 2025). An inflammatory bowel disease involving the mucosal surface of the large intestine and rectum. "It is speculated that genetic variants of SMAD2/3/4/7 might alter the balance of differentiation between Th17 and T, resulting in the development of inflammatory bowel disease, including ulcerative colitis." (PMID 32934961, 2020).
Wilms tumor (3 papers, 2019 to 2024). An embryonal neoplasm characterized by the presence of epithelial, mesenchymal, and blastema components. "We demonstrated that miRNA-140-5p participates in the progression of Wilms’ tumor by targeting the TGFBRI/SMAD2/3 and the IGF-1R/AKT signaling pathways." (PMID 31035970, 2019). "To verify importance of both proteins in Wilms’ tumor, we detected expression of SMAD2/3 and p-AKT and found that both were highly expressed in the tumor tissues compared with adjacent normal tissue." (PMID 31035970, 2019). "Also, agents targeting the IGF-1R/AKT and TGFBRI/SMAD2/3 signaling pathways have demonstrated anti-tumor activity in preclinical studies and are being evaluated in clinical trials for their efficacy and safety in Wilms tumor patients." (PMID 39062028, 2024). "Our data suggested that miR-140-5p regulated Wilms’ tumor progression and TGFBRI/SMAD2/3 and IGF-1R/AKT signaling pathways participate in this process." (PMID 31035970, 2019). "miRNA-140-5p expression was downregulated in Wilms’ tumor tissues, and miR-140-5p could regulate Wilms’ tumor progression via the IGF-1R/ AKT and TGFBRI/SMAD2/3 pathways and that it might have tumor suppressive functions with regard to Wilms’ tumor progression and metastasis." (PMID 31035970, 2019).
acute promyelocytic leukemia (2 papers, 2015 to 2026). An aggressive form of acute myeloid leukemia (AML), characterized by arrest of leukocyte differentiation at the promyelocyte stage, due to a specific chromosomal translocation t(15;17) in myeloid cells. "In acute promyelocytic leukemia (APL), HF suppresses leukemia growth and angiogenesis via inhibition of SMAD2 signaling." (PMID 41491331, 2026).
adenomyosis (2 papers, 2017 to 2019). The growth of endometrial tissue inside the muscular wall of the uterine corpus. "We further evaluated the total Smad2 and total Smad3 staining of control and each type of adenomyosis." (PMID 29253010, 2017). "In our study cases, TGF-β1/ TGF-β1 receptor expressions with a higher Smad3/Smad2 ratio was observed in Subtype II adenomyosis cases, while Subtype I cases showed no significant modification of TGF-β1signaling proteins." (PMID 29253010, 2017).
allergic asthma (2 papers, 2018 to 2024). A asthma with a basis in a pathological type I hypersensitivity reaction. "We establish that scutellarin effectively improves the allergic asthma conditions by regulating the Smad2/Smad3 and MAPK pathways." (PMID 38168709, 2024).
Arrhythmia (2 papers, 2020). Any cardiac rhythm other than the normal sinus rhythm. "A mouse model with cardiomyocyte-specific Jup mutation showed cardiac arrhythmia and massive cardiac fibrosis, as well as dramatically increased expressions of TGFβ1 and phospho-Smad2 (P-Smad2) in the heart." (PMID 32878278, 2020).
Ataxia (2 papers, 2019 to 2020). Ataxia refers to impaired coordination of voluntary muscle movement. "Smad2 depletion in mice also caused cerebellar foliation anomalies and ataxia." (PMID 32000863, 2020).
Atrophy (2 papers, 2022). Any weakening or degeneration, especially through lack of use. "Muscle atrophy induced by the TGF-β member myostatin involves Smad2/3 signaling that activates MAFbx expression and downregulates mTOR signaling." (PMID 36402791, 2022).
cardiac interstitial fibrosis (2 papers, 2021 to 2023). "Increased TGF-β1/Smad2/3 signaling cascade is involved in cardiac interstitial fibrosis and cardiac left ventricular remodeling." (PMID 34658906, 2021).
cataract (2 papers, 2018 to 2025). Partial or complete opacity of the crystalline lens of one or both eyes that decreases visual acuity and eventually results in blindness. "Since quiescent fibre cells in NT mice minimally express TGF-β receptors and ligands, p-Smad2 detection is an adequate criterion to evaluate TGF-β signaling activation in K14E6 cataracts." (PMID 29888254, 2018). "Snail is considered an effector of TGF-β-induced EMT and it is activated by TGF-β signaling through the action of p-Smad2/3 and Smad4 in mouse lens epithelial cells; consistent with these reports, we also observed increased expression of Snail mRNA in K14E6 cataracts." (PMID 29888254, 2018). "Notably, we observed an increased nuclear signal of p-Smad2 in transgenic mice cataracts, suggesting that the TGF-β pathway is active in K14E6 cataracts." (PMID 29888254, 2018).
cerebral infarction (2 papers, 2022). An ischemic condition of the brain, producing a persistent focal neurological deficit in the area of distribution of the cerebral arteries. "Compared with those of sham operation and control groups, mRNA levels of ALDH1, Smad2, and Smad4 were markedly higher in cerebral infarction group, whilst p21 level was lower (P < 0.05)." (PMID 35909581, 2022). "1,25-D3 reduced cerebral infarction volume, increased the recovery of CBF and expressions of VDR, TGF-β, p-Smad2, p-Smad3, and VEGF, significantly increased IB4+ tip cells and CD31+ vascular length in the peri-infarct area compared with the DMSO group." (PMID 35369317, 2022).
Cerebral ischemia (2 papers, 2022 to 2023). Restriction of arterial blood supply to the brain associated with insufficient oxygenation to support the metabolic requirements of the tissue. "TGF expression was increased in an undifferentiated SH-SY5Y cell model of cerebral ischemia, together with increased phosphorylation of SMAD2 and SMAD3." (PMID 37380886, 2023).
cervical tumor (2 papers, 2013 to 2024). "Several studies have reported reduced expression of SMAD2 in human cervical tumor samples." (PMID 38200081, 2024).
Chagas disease (2 papers, 2022 to 2025). A parasitic infection caused by Trypanosoma cruzi. "CircRNA_400090 could regulate the expression of FOXO1, CCND2 and SMAD2 to participate the pathways of hsa04068: FoxO signalling pathway or hsa05142: Chagas disease (American trypanosomiasis)." (PMID 35840955, 2022). "These researchers found that many of these piRNAs, such as hsa_piR_016828 and the novel npiR_17, target genes crucial in the fibrotic and inflammatory processes characteristic of Chagas disease, including ICAM1 and SMAD2." (PMID 41295584, 2025).
chronic myeloid leukemia (2 papers, 2024 to 2025). "In chronic myeloid leukemia (CML) cells, they showed that TRPM7 kinase regulates AKT and mothers against decapentaplegic homolog 2 (SMAD2) pathways leading to modulated cyclooxygenase-2 (COX-2) expression." (PMID 41395111, 2025). "Moreover, bosutinib, a tyrosine kinase inhibitor, is perhaps the best candidate identified, as it is already in use against chronic myeloid leukemia and was found to target five upregulated proteins (CDC37, CDKN1B, GRB2, RASSF1, and SMAD2)." (PMID 39202022, 2024).
colon adenocarcinoma (2 papers, 2013 to 2024). "Overall, normal colonic epithelial cells display higher nuclear Smad2 phosphorylation and lower VEGFA expression than adenocarcinomas, supporting the view that expression of VEGFA inversely correlates with TGF-beta signaling in human colonic adenocarcinoma." (PMID 23536895, 2013).
cystic kidneys (2 papers, 2016 to 2020). "PCNA, β‐catenin, and Smad2 were elevated in cystic kidneys compared to age‐matched controls by 18 days of age, and the phosphorylated forms of both Erk and ribosomal protein S6 were elevated compared to wild‐type controls by 26 days of age." (PMID 27356569, 2016). "The TGFβ/Smad2 pathway is known to be hyperactivated in kidneys lacking Pkd1 and to induce kidney fibrosis, a prevalent feature of cystic kidneys." (PMID 32651191, 2020).
cystitis (2 papers, 2019 to 2025). Inflammation of the urinary bladder. "Three key proteins of the TGF-β/Smad pathway—TGF-β, p-Smad2, and p-Smad3—are upregulated in the bladders of CYP-induced cystitis rats (all P < 0.05)." (PMID 40271070, 2025).
embryonic carcinoma (2 papers, 2017 to 2021). "At a 10 μM concentration, two discovered bicyclic peptides completely suppressed NODAL-induced phosphorylation of SMAD2 in P19 embryonic carcinoma cells." (PMID 34349940, 2021). "By combining RNA-seq with ChIP-seq for SMAD2, two distinct forms of Pol II, histone H3 acetylations and total H3 in P19 embryonic carcinoma cells, we have addressed how a single pathway induces a program of gene expression that is constantly remodeled over time." (PMID 28191871, 2017).
folate deficiency (2 papers, 2023 to 2025). A nutritional condition produced by a deficiency of FOLIC ACID in the diet. "Activation of these pathways by phosphorylated STAT3 and Smad2/3 were affected by both HFF diet and folate deficiency." (PMID 37630806, 2023). "The positive correlation between leptin and phosphorylated STAT3 ratio, as well as TGF-β1 and phosphorylated Smad2/3 ratio in renal tissues, revealed the mechanisms of effects of the HFF diet and folate deficiency." (PMID 37630806, 2023). "Both HFF and folate deficiency significantly increased the phosphorylation of STAT3 and Smad2/3, suggesting synergistic effects of HFF−f on chronic renal inflammation and fibrosis." (PMID 37630806, 2023).
Granuloma (2 papers, 2015 to 2024). A compact, organized collection of mature mononuclear phagocytes, which may be but is not necessarily accompanied by accessory features such as necrosis. "Consistent with this, we found that although the mRNA expression of SMADs 2 and 3 were not elevated in FCMs, levels of phosphorylated, nuclear localised SMAD2 were increased in granuloma FCMs relative to NFMs and in plaque FCMs, suggesting that TGFβ1 signalling was occurring." (PMID 26197235, 2015).
head and neck cancer (2 papers, 2010 to 2017). A primary or metastatic malignant neoplasm affecting the head and neck. "In addition, SMAD2 mutations in human head and neck cancer have been reported." (PMID 28938536, 2017). "Our finding regarding the association between lack of Smad2 expression and a favourable clinical outcome is in disagreement with previous studies done in head and neck cancer as well as other tumor types." (PMID 20462450, 2010).
hepatic (2 papers, 2017 to 2018). "They further showed that phosphorylated Stat3 and IL-6 were reduced in ConA-induced hepatitis, whereas p21 and Smad2 increased." (PMID 28330461, 2017).
hepatic diseases (2 papers, 2023 to 2024). "The modulation of the balance between TGF-β signaling to Smad2/3 vs. pAkt (by TGF-β or EGF) has potential implications for hepatic diseases and malignancies." (PMID 38168942, 2024). "In addition, signalling pathways such as Akt/FoxO1, AMPK, PPAR γ, Smad2/3 and Caspase-3 have been shown to be vital molecular targets for FA involvement in improving various liver diseases." (PMID 37324465, 2023).
hyperuricemia (2 papers, 2023 to 2024). An abnormally high level of uric acid. "In particular, hyperuricemia contributes to MI progression by decreasing fibroblast-derived lumican levels to activate the TGFβ/Smad2/3 signaling pathway, subsequently promoting fibroblast transition to myofibroblasts and enhancing adverse cardiac remodeling." (PMID 39482719, 2024). "Moreover, the expression of molecules downstream of the TGF-β signaling pathway, p-SMAD2/3, as determined by western blotting, was increased in hyperuricemia-related MI mice." (PMID 39482719, 2024). "However, hyperuricemia lowered lumican expression in MI mice and activated the TGFβ/Smad2/3 signaling pathway in cardiac fibroblasts to trigger adverse cardiac remodeling." (PMID 39482719, 2024).
intervertebral disc degeneration (2 papers, 2016 to 2022). "Therefore, the TGF‐β1/Smad2/3 pathway might play a critical role in the ability of PRP to retard intervertebral disc degeneration." (PMID 27061332, 2016). "This suggested that PRP could activate the biological activity of Smad2/3, which effectively promotes the synthesis and secretion of collagen II and other matrix components that contribute to the structural and functional recovery of intervertebral disc degeneration." (PMID 27061332, 2016). "Based on the in vivo and in vitro results, PRP could retard intervertebral disc degeneration, and the TGF‐β1/Smad2/3 pathway plays a key role in the process." (PMID 27061332, 2016).
intestinal tumor (2 papers, 2011 to 2020). "In Smad2/APC (adenomatous polyposis coli) double heterozygous mice, Smad2 deletion accelerates APC mutation-induced intestinal tumor growth and invasion but does not increase the number of tumors." (PMID 22204491, 2011).
Intracranial Aneurysm (2 papers, 2018 to 2025). "Characteristics of the datasets used to test the association between intracranial aneurysms, and the genes PKD1 and SMAD2." (PMID 40172005, 2025).
invasive breast carcinoma (2 papers, 2012 to 2021). A carcinoma that infiltrates the breast parenchyma. "Increased SMAD2 expression has been reported in invasive breast carcinoma, which promotes the signal translocation to the nucleus to promote the expression of target genes." (PMID 34297787, 2021). "Cthrc1 is a Smad2/3 (TGF-β signalling) inhibiting Wnt signalling modulator that is differentially expressed in invasive breast cancer and several solid tumors." (PMID 22260314, 2012).
ischemia (2 papers, 2021 to 2022). A hypoperfusion of the BLOOD through an organ or tissue caused by a PATHOLOGIC CONSTRICTION or obstruction of its BLOOD VESSELS, or an absence of BLOOD CIRCULATION. "Previous experiments in rats exhibited upregulated Smad2/3 in the penumbra following ischemia/reperfusion, and those effects negatively correlated with cell apoptosis." (PMID 35015765, 2022).
ischemic stroke (2 papers, 2021 to 2022). A stroke disorder caused by obstruction of blood flow to the brain, due to thrombotic (local blood clot formation) or embolic (due to a blood clot or other material traveling from another site) event. "As a remodeling factor from microglia, numerous studies suggest TGF-β1 which is associated with the TGF-β/Smad2/3 signaling pathway may exert a protective effect on angiogenesis, axonal outgrowth, anti-apoptosis, and immunomodulation in ischemic stroke." (PMID 34753919, 2021). "To analyze the role of EVs from OGD-preconditioned microglia on the regulation of the TGF-β/Smad2/3 pathway in ischemic stroke, we studied TGF-β, p-Smad2/3 and Smad2/3 protein expression in mice submitted to 60 min of MCAO." (PMID 34753919, 2021).
kidney injuries (2 papers, 2022 to 2024). "Hyperoxia-induced kidney injuries are influenced by several molecular factors, including hypoxia-inducible factor-1α and interleukin-6/Smad2/transforming growth factor-β, and Wnt/β-catenin signaling pathways; these are key to cell proliferation, tissue inflammation, and cell membrane repair." (PMID 35955627, 2022).
liver cirrhosis (2 papers, 2020 to 2024). "The enhanced expression of Smad2 and Smad3 was observed after the induction of liver cirrhosis." (PMID 32928296, 2020). "Moreover, IL-35 might suppress the activation of the TGF-β1/Smad2/3 signaling pathway and inhibit the differentiation of Th17 cells in HBV-related liver cirrhosis patients, thereby suppressing inflammation, apoptosis, and fibrosis." (PMID 39772266, 2024).
lung squamous cell carcinoma (2 papers, 2023 to 2024). "The TGF-β1 transcription factor SMAD3 is epigenetically repressed in tumour-associated fibroblasts (TAFs) from lung squamous cell carcinoma (SCC) but not adenocarcinoma (ADC) patients, which elicits a compensatory increase in SMAD2 that renders SCC-TAFs less fibrotic." (PMID 36572730, 2023).
meningioma (2 papers, 2012 to 2022). A generally slow growing tumor attached to the dura mater. "The results showed that coculture with M2-MDEs increased the phosphorylation level of Smad2/3 in meningioma cells." (PMID 35637794, 2022). "The western blotting of cytoplasmic and nuclear proteins revealed increased nuclear translocation of Smad2 and Smad3 in meningioma cells cocultured with M2-MDEs." (PMID 35637794, 2022). "TGFβ signaling pathway was also found activated in fibroblastic meningioma, since multiple key genes in the pathway were up-regulated in tumor tissues by qRT-PCR, including TGFB2 (4.95-fold), TGFBR1 (2.43-fold), SMAD2 (2.82-fold), and SMAD4 (3.24-fold)." (PMID 23285163, 2012).
multiple sclerosis (2 papers, 2017 to 2025). A progressive autoimmune disorder affecting the central nervous system resulting in demyelination. "Its overexpression is also related to T helper cell differentiation in multiple sclerosis, possibly by a mechanism involving SMAD2, GATA3, and FOXO3 genes, whose participation in Th17 cell differentiation, Treg inhibition, and/or other T helper pathways has been underlined." (PMID 29349090, 2017).
muscular dystrophy (2 papers, 2020 to 2024). Muscular dystrophy (MD) refers to a group of more than 30 genetic diseases characterized by progressive weakness and degeneration of the skeletal muscles that control movement. "The activation of SMAD2/3 upregulates expression of ECM-associated genes, and the D2 strain carries an allele of Ltbp4 that enhances active TGF-β, contributing to the exacerbation of muscular dystrophy by the D2 background." (PMID 38175727, 2024). "Inhibition of myostatin- and activin-mediated SMAD2/3 signaling using ligand traps, such as soluble receptors, ligand-targeting propeptides and antibodies, or follistatin can increase skeletal muscle mass in healthy mice and ameliorate wasting in models of cancer cachexia and muscular dystrophy." (PMID 33250771, 2020).
myocarditis (2 papers, 2017 to 2020). Myocarditis is a condition that is characterized by inflammation of the heart muscle (myocardium). "A number of studies have shown that inhibition of the TGF-β1/Smad2/3 signaling pathway relieves the cardiomyocyte apoptosis and fibrosis reactions in myocarditis." (PMID 33414684, 2020). "Compared with the myocarditis group, the expression of Smad2 and p-Samd2 protein tended to decrease in the BMSCs treatment group, but the difference between the two groups was not statistically significant." (PMID 29362568, 2017).
myopia (2 papers, 2021 to 2025). "Elevated hypoxia-induced IL-6 has been demonstrated to exacerbate myopia by promoting scleral remodeling through the TGF-β1/Smad2/MMP-2 pathway, supporting the hypothesis that metabolic inflammation contributes to myopia through a “metabolic-immune-hypoxia” network." (PMID 41191163, 2025).